LINC01473 (long independently transcribed non-coding RNA 1473)
Gene: Long non-coding RNA gene on chromosome 2 (186,032,041 to 186,486,584, reverse strand). Ensembl gene ENSG00000237877.
Diseases named in the same sentence as LINC01473 in open-access papers:
LINC01473 is named in the same sentence as 2 diseases in open-access papers, as found by Europe PMC text mining. Sharing a sentence is not in itself a finding about the gene and the disease. The quoted sentences say what the papers report.
childhood cancer (1 paper, 2020). "A deletion of the LINC01473 gene present in a 2N patient was reported to be deleted in a childhood cancer patient by Krepischi." (PMID 32577795, 2020).
multiple myeloma (1 paper, 2023). "Aberrant expression of LINC01473 in osteoblasts facilitated imbalanced bone formation and resorption in multiple myeloma (MM), which influenced immune escape of MM." (PMID 36816017, 2023).